CNBD1 (cyclic nucleotide binding domain containing 1)
Synonyms: FLJ35802
Tractability: No criterion of Open Targets' tractability assessment is met for any kind of drug.
Gene: Protein-coding gene on chromosome 8 (86,866,415 to 87,615,219, forward strand). Ensembl gene ENSG00000176571.
Genetic constraint (gnomAD): Loss-of-function variants: 13 observed, 11.06 expected, observed/expected ratio (o/e) 1.18, 90% interval 0.76 to 1.78. The upper end of that interval is the gene's LOEUF score, 1.78, which puts it in group 6 of 6, group 1 being the genes least tolerant of losing a copy. Missense variants: 195 observed, 149.47 expected, observed/expected ratio (o/e) 1.3, 90% interval 1.16 to 1.47. Synonymous variants: 62 observed, 55.04 expected, observed/expected ratio (o/e) 1.13, 90% interval 0.92 to 1.39.
Homologues: Orthologues: chimpanzee CNBD1 (99% identical), macaque CNBD1 (92% identical), pig CNBD1 (72% identical), dog CNBD1 (70% identical), rabbit CNBD1 (59% identical), rat Cnbd1 (58% identical), mouse Cnbd1 (56% identical), zebrafish cnbd1 (27% identical). Paralogues in human: PRKAR2A (16% identical), PRKAR2B (16% identical), PRKAR1B (15% identical), PRKAR1A (15% identical).
Diseases named in the same sentence as CNBD1 in open-access papers:
CNBD1 is named in the same sentence as 6 diseases in open-access papers, as found by Europe PMC text mining. Sharing a sentence is not in itself a finding about the gene and the disease. The quoted sentences say what the papers report.
Ciliopathies (1 paper, 2023). "Genes in state 3 were enriched for Ciliopathies, marked by NKAIN3 and CNBD1." (PMID 36929025, 2023).
liver cancer (1 paper, 2021). An epithelial or non-epithelial malignant neoplasm that arises from the liver. "The corresponding genes of middle-stage CNV events including MYC, CNBD1, HEY1, RUNX1T1, CDH17, high expression of HEY1 gene promotes self-renewal of tumor stem cells, especially in liver cancer." (PMID 34453042, 2021).
metastatic tumor (1 paper, 2015). "In contrast, seven other non-synonymous or frameshift mutations (in genes UGT3A2, PLCG1, OR10K1, COL9A1, MAGEA6, CNBD1 and LG14) were detected only in the metastatic tumor, indicating a selection and proliferative advantage of cells with the diverse genotype under sunitinib treatment." (PMID 26474454, 2015).
cancer (3 papers, 2016 to 2023). A tumor composed of atypical neoplastic, often pleomorphic cells that invade other tissues. "Seven genes were expressed in non-cancerous tissues only, including LINC01612 (TSG), FAM3D (inflammation), HCN1, and CNBD1 (mutation in cancer) and three other genes." (PMID 37509325, 2023).
tumor (2 papers, 2021 to 2023). "Sixteen nearby genes showed higher expression in non-cancerous tissues, including seven with almost no expression in tumor (HCN1, SLC22A2, FAM3D, LRFN5, LINC01612, LINC02512, and CNBD1)." (PMID 37509325, 2023).
CNBD1 also shares sentences with these, for which no sentence is quoted: gastric cancer (1 paper).